FTO (FTO alpha-ketoglutarate dependent dioxygenase)
Diseases named in the same sentence as FTO in open-access papers (continued):
Sharing a sentence is not in itself a finding about the gene and the disease.
Obesity (continued). "A growing number of studies have recently examined whether there are interaction effects between those lifestyle factors and FTO genetic variants on obesity risk." (PMID 26908368, 2016). "Although there are a handful of studies with mixed populations, including Latinos, these studies including our own, have only examined the association between FTO genetic variants and obesity-related phenotypes such as body mass index (BMI), waist circumference, or body composition." (PMID 26908368, 2016). "In the case of the promising candidate, SNPs within the NYD-SP18 gene area, the potential physiological link between this gene and obesity remain unknown; however, this applies to some extent to most obesity-associated genes (such as TMEM18 or FTO)." (PMID 27237450, 2016). "Our findings suggest that the association between FTO SNPs and obesity might be influenced by carbohydrate and dietary fibre intake and physical inactivity." (PMID 27274759, 2016). "Even though our study has a small sample size compared to the large European cohorts, we were still able to confirm the previously reported interactions between FTO variants and dietary intake and physical activity on obesity traits in this Asian Indian population." (PMID 27274759, 2016). "The study also provides evidence that low levels of physical activity may accentuate the risk of obesity by the FTO SNP rs8050136." (PMID 27274759, 2016). "Single-nucleotide polymorphisms (SNPs) of the fat mass and obesity associated (FTO) gene are linked to obesity, but how these SNPs influence resting-state neural activation is unknown." (PMID 26924971, 2016). "Concluding from the observed association of IRX3 expression with FTO obesity risk variants and UCP1 expression in adipocytes of lean children, one may expect increased IRX3 expression in obese subjects." (PMID 27560134, 2016). "Another group reported that obesity variants within the FTO gene formed a long-range connection with IRX3, which was located downstream from FTO, and deficiency in this gene resulted in 25–30% body weight loss, thus questioning a direct role for FTO in obesity." (PMID 27249342, 2016). "A SNP in the FTO locus was further nailed down as the obesity-causing variant." (PMID 26880991, 2016). "Therefore, further research should include studies on the effects of omega-3 fatty acids in blocking the effects of the risk allele (rs 1421085), which appears to be responsible for the association between the first intron of FTO gene and obesity in humans." (PMID 26950145, 2016). "Studies in European populations have shown that physical activity and dietary intake may modify the association of the FTO variant with obesity-related traits." (PMID 27274759, 2016). "The causal role of the FTO protein in obesity is supported by evidence obtained from transgenic mice; however, the underlying molecular pathways pertaining to the role of FTO in obesity have yet to be established." (PMID 27827997, 2016). "Association of intron 1 FTO SNPs with obesity grade, stratified by gender, in MMs." (PMID 26726774, 2016). "This could explain why carriers of the obesity predisposing SNPs in FTO not only consume more calories during test meals but also show an alteration in nutrient preference and a higher dietary protein intake." (PMID 26907388, 2016). "Fat mass and obesity associated (FTO) is a novel gene strongly associated with the risk of obesity." (PMID 26907332, 2016). "With consistent replications of the associations between FTO genetic variants and obesity-related phenotypes, it is of growing interest whether these genetic effects on obesity are modified by lifestyle factors such as physical activity (PA)." (PMID 26908368, 2016). "Our data suggest that FTO SNPs make differential contributions to obesity risk and support the hypothesis that gender differences in the mechanisms involving these variants may contribute to disease development." (PMID 26726774, 2016).
Obesity (continued). "Whether the effects of FTO variants on the susceptibility to T2D are mediated by their effects on obesity/adiposity remains controversial." (PMID 27820839, 2016). "For instance, individuals homozygous for the higher-risk allele, AA, of single nucleotide polymorphism (SNP) rs9939609 in the FTO gene FTO weighed, on average, 3 kg more and had 1.7-fold increased odds of having obesity compared with those homozygous for the lower-risk allele, TT." (PMID 26851191, 2016). "Interestingly, obesity-associated FTO risk alleles have been discussed as candidate thrifty alleles, which have been driven to high frequency by positive selection." (PMID 27560134, 2016). "In the present study, we found a significant interaction between the FTO SNP rs8050136 and carbohydrate energy percentage on obesity, where the minor allele carriers had higher risk of obesity among those in the highest tertile of carbohydrate energy percentage." (PMID 27274759, 2016). "In our MM population, we detected strong associations between all five FTO SNPs and obesity." (PMID 26726774, 2016). "Taken together, this suggests an FTO-associated susceptibility to obesity." (PMID 26907332, 2016). "The FTO gene encodes for an alpha-ketoglutarate-dependent dioxygenase, playing a role in growth and development, and has been reliably associated with the related conditions of type 2 diabetes, BMI, adiposity and other obesity-related traits." (PMID 28018425, 2016). "Individually, we tested whether FTO, the strongest known susceptibility locus for common obesity associates with VO2max and we found an inverse, adiposity-mediated association." (PMID 27846319, 2016). "The single nucleotide polymorphism rs9939609 of the gene FTO, which encodes fat mass and obesity–associated protein, is strongly associated with obesity and type 2 diabetes (T2D) in multiple populations; however, the underlying mechanism of this association is unclear." (PMID 27249024, 2016). "Understanding the influence of the FTO gene on susceptibility to obesity might help improve current research on prevention strategies to fight obesity based on individual genetics." (PMID 26924971, 2016). "A variety of genomic alterations, e.g., in FTO or the genes that functionally interact with it, could confer susceptibility for obesity." (PMID 27390851, 2016). "Genetic variants in the fat-mass- and obesity-associated FTO gene are associated with MDD." (PMID 26125155, 2015). "Our results suggest that several FTO variants may underlie parent-of-origin effects modulating the risk of obesity." (PMID 25793382, 2015). "In summary, the obesity-risk variant in FTO intron 1 was inversely associated with the SE type, independent of BMI, which corresponded well with the characteristics of the SE type, such as the lowest body mass and lowest susceptibility to metabolic disorders among the constitutional types." (PMID 25888059, 2015). "The fact that the obesity-associated FTO SNPs are intronic has led to the notion that the SNPs may affect obesity through influencing the expression of genes proximal to FTO in the locus, namely, RPGRIP1L, IRX3, and IRX5." (PMID 26788058, 2015). "A third explanation for heterozygote advantage could be even the involvement of an additional factor or an interaction of the IRX3 promoter with the obesity-associated SNP region of FTO." (PMID 26431034, 2015). "Our results suggest that the obesity risk transmitted by several FTO variants may depend on the parental origin of the allele." (PMID 25793382, 2015). "As an example, altered FTO methylation and gene regulation may provide a link between obesity-associated leptin resistance following IUGR and rapid postnatal weight gain." (PMID 26402696, 2015). "These SNPs were chosen as representative of the obesity status in Western populations (as no comprehensive studies are available yet for the Arabian populations) and because close or within genes whose association to obesity has been well established (e.g., FTO, MC4R)." (PMID 25890290, 2015).
Obesity (continued). "In various populations FTO has been confirmed to be a major risk gene promoting obesity." (PMID 26691922, 2015). "The genetic obesity predisposition (FTO rs9939609 gene variant in this case) may develop into the disease but not necessarily." (PMID 25866584, 2015). "Indeed, recent data focussing on obesity associated variants within FTO have implicated two neighbouring genes, RPGRIP1L and IRX3, as having a functional link between the SNP and the observed human phenotypes." (PMID 25830092, 2015). "In addition to leptin, a further candidate re epigenetic regulation is that of the fat mass and obesity-associated (FTO) gene." (PMID 26402696, 2015). "A recent study in rats found that FTO mRNA expression in the hypothalamus was increased in offspring following maternal obesity and was associated with a predisposition to high fat diet induced obesity in adulthood, potentially due to increased food intake." (PMID 26788058, 2015). "Furthermore, two additional independent FTO variants are identified as associated with both obesity and OA, and both variants are ranked higher by ABFs rather than P‐values." (PMID 26411566, 2015). "Thus, it remains a possibility that the obesity associated with the SNP is mediated by FTO during development or in peripheral tissues." (PMID 26788058, 2015). "Mouse models have been informative; knockdown of FTO in mice results in reduced fat mass, suggesting that the susceptibility to obesity could be through over-expression of FTO." (PMID 26642925, 2015). "Interestingly, Dina and colleagues demonstrated that FTO SNPs are associated not only with adult obesity but also with childhood obesity." (PMID 26788058, 2015). "We hypothesized that there may be variants within the robustly replicated fat mass and obesity associated (FTO) gene that may confer different risk for obesity depending on transmission from mother or father." (PMID 25793382, 2015). "Overall, these animal experiments suggest that the genes IRX3 and RPGRIPL1 may mediate at least in part the association of SNPs in FTO with obesity." (PMID 25825681, 2015). "However, the mutant FTO A allele was found more in correlation with obesity in adults than in children, both being statistically significant." (PMID 25866584, 2015). "Recent reports suggest that vitamin D is a modifiable risk factor for the obesity and the obesity inducing effects of the FTO gene (name derived from the Fused Toes and Other abnormalities observed in the mice with the specific gene deletion) were observed more in patients with VDD." (PMID 26131437, 2015). "In fact, the association between FTO SNPs and obesity peaks during early adolescence and tapers off thereafter, suggesting that FTO SNPs may impact obesity by influencing events during the developmental period." (PMID 26788058, 2015). "Furthermore, the obesity-associated FTO allele represses mitochondrial thermogenesis in adipocyte precursor cells in a tissue-autonomous manner associated with a shift of energy-dissipating beige adipocytes to energy-storing white adipocytes." (PMID 26691922, 2015). "In conclusion, we elucidated that the obesity-risk variant of FTO, rs7193144, was inversely associated with the SE type constitution, independent of BMI, on the basis of SCAT probability values from two-stage analyses of GWAS and replication analysis in Koreans." (PMID 25888059, 2015). "In conclusion, the FTO rs9939609 polymorphism has been identified as a common gene variant in our Romanian Caucasian cohort, proving a high association with all the parameters of obesity and obesity comorbidities." (PMID 25866584, 2015). "FTO rs9939609 has been reported to be associated with obesity in many other papers." (PMID 26146447, 2015). "Results show that the positive association of FTO rs9939609 with BMI and the risk of obesity may change from childhood into adolescence in this Chinese population." (PMID 24827155, 2014). "The variant most strongly associated with obesity/BMI is found in the FTO locus." (PMID 24719615, 2014).
Obesity (continued). "Several independent, genome-wide, association studies have recently identified a strong correlation between fat mass and obesity-associated (FTO) polymorphisms and obesity-related parameters (body mass index [BMI], total body weight, and hip circumference) in adults and children." (PMID 25539997, 2014). "Cross-sectional Associations of FTO rs9939609 with Obesity Stratified by Sex and Pubertal Stage." (PMID 24827155, 2014). "However, our research indicates, when assessing, the risk of overweight and obesity carriage of the A allele in the FTO variant rs9939609 should be taken into account." (PMID 25214838, 2014). "Associations of the candidate FTO SNPs with risk of obesity in a population of school-age children." (PMID 25251416, 2014). "Five common variants: rs17782313 and rs1770633 (melanocortin 4 receptor (MC4R); rs7566605 (insulin induced gene 2 (INSIG2); rs9939609 and rs1121980 (fat mass and obesity associated (FTO) were genotyped in 2 cohorts of Swedish women: PEAK-25 (age 25, n = 1061) and OPRA (age 75, n = 1044)." (PMID 24516669, 2014). "Among these targets, the gene FTO (fat mass and obesity associated) encodes a Fe(II)- and 2-oxoglutarate-dependent nucleic acid demethylase that regulates lipid metabolism, and the possibility that its expression is negatively regulated by miR-33 in the chicken liver was therefore further studied." (PMID 24626192, 2014). "Novel phenotype associations with obesity-associated FTO variants included fibrocystic breast disease (rs9941349, OR = 0.81, 95% CI = 0.74–0.91, p = 5.41 × 10−5) and trends toward associations with non-alcoholic liver disease and gram-positive bacterial infections." (PMID 25177340, 2014). "In addition, FTO polymorphisms in intron 1 have been linked to a range of human cancers, yet a recent meta-analysis study suggested that except for pancreatic cancer the increased cancer risk is rather associated to obesity than the FTO polymorphism itself." (PMID 25014650, 2014). "Single nucleotide polymorphisms (SNPs) that cluster in the first intron of the FTO gene were first discovered in a genome-wide association study (GWAS) for type 2 diabetes mellitus, and, subsequently, other GWAS reported that the FTO polymorphisms were associated with obesity." (PMID 25367448, 2014). "A meta-analysis of the two study populations replicated the well-described associations between FTO variants and obesity (odds ratio [OR] = 1.25, 95% Confidence Interval = 1.11–1.24, p = 2.10 × 10−9) and FTO variants and T2D (OR = 1.14, 95% CI = 1.08–1.21, p = 2.34 × 10−6)." (PMID 25177340, 2014). "The FTO protein regulates energy metabolism to increase the obesity risk." (PMID 24466303, 2014). "Markers flanking the SSC6a QTL region are located in the FTO gene (fat mass and obesity associated), where a polymorphism has previously found to be associated with RFI in Yorkshire pigs, but which was subsequently not reported as significantly associated with RFI in a GWAS in that same population)." (PMID 24528607, 2014). "Obesity-associated genes that show altered expression in FTO-4 mice." (PMID 24842286, 2014). "Evidence from several studies indicates that the association between FTO variants and obesity-related traits may be age-dependent and may differ by sex." (PMID 24827155, 2014). "In addition, obesity affects the brain via promotion of inflammatory processes, with a substantial contribution of genetic variants such as Fat Mass and Obesity (FTO) gene." (PMID 25984353, 2014). "Among the susceptibility genes, the “fat mass and obesity associated” (FTO) gene may be one of the molecular determinants linking both pathologies." (PMID 24410832, 2014). "At present, it has been reported that FTO gene influence PCOS mainly via the association with obesity or obesity-related parameters, such as BMI, body weight, fat mass and some other metabolism-related traits, such as insulin resistance, impaired fasting glucose, glucose intolerance." (PMID 24466303, 2014).